G3BP1 (G3BP stress granule assembly factor 1)
Diseases named in the same sentence as G3BP1 in open-access papers (continued):
Sharing a sentence is not in itself a finding about the gene and the disease.
tumor (80 papers, 2011 to 2026). "We also demonstrate that the loss of G3BP1 during senescence generates a SASPless phenotype which impairs SASP-dependent tumor growth and metastasis in vitro and in vivo." (PMID 33020468, 2020). "Since enhanced tumor cell migratory capacity is one of the characteristics of tumor metastasis, further tests based on loss-of-function approach were used to examine the effects of G3BP1 on RCC tumor cell mesenchymal phenotypes." (PMID 29717134, 2018). "Thus, high levels of AEP and G3BP1 truncations in OS and glioma tumor tissues are strongly associated with tumor malignancy and poor patient prognosis." (PMID 40858563, 2025). "G3BP1 mutations enhance translational control under stress and promote tumor survival." (PMID 40785597, 2025). "Furthermore, we demonstrated that BIN1 loss inhibits CD8+ T cell infiltration by stabilizing G3BP1, which in turn induces the establishment of an immunosuppressive microenvironment and facilitates tumor progression." (PMID 40346580, 2025). "In addition, a previous study identified that G3BP1 is associated with the tumour response to the Akt inhibitor MK-2206." (PMID 34044876, 2021). "Finally, the regulatory axis of USP21/G3BP1 was demonstrated to be aberrantly activated in ESCC tumor tissues and closely associated with advanced clinical stages and unfavorable prognoses, which provides a promising therapeutic strategy targeting USP21/G3BP1 axis for ESCC patients." (PMID 38906857, 2024). "Thus, a loss of tumor suppressive function of G3BP1 or DDX41 may lead to leukemic evolution in del(5q)." (PMID 28031539, 2017). "In vivo, disruption of the NUP93/SOX2/G3BP1 axis suppressed tumor growth and synergized with gemcitabine." (PMID 41896201, 2026). "Fluorescence tissue staining revealed a substantial increase in the number of CD8-positive T cells within tumor tissues in the BIN1-WT + sh-G3BP1 group, compared to the BIN1-WT group." (PMID 40346580, 2025). "Consistent with in vitro proliferation results, tumor volumes were significantly decreased in G3BP1‐KO xenografts compared with the control xenografts." (PMID 40536321, 2025). "Tumor formation assays demonstrated that tumorigenicity in mice from the BIN1-WT + sh-G3BP1 group was markedly reduced compared to the BIN1-WT group." (PMID 40346580, 2025). "In contrast, STAT1 overexpression partially attenuated the tumor-promoting effects of G3BP1 overexpression and its suppression of CD8+ T cell infiltration." (PMID 40346580, 2025). "G3BP1/G3BP2 double-knockout (dKO) U2OS cells was further constructed, which were rescued with G3BP1-WT, G3BP1-N258A, and G3BP1-N309A to further validate that the cleavage sites at N258 and N309 of G3BP1 actually occurred in tumor cells during drug treatment." (PMID 40858563, 2025). "As chemotherapeutic drug-induced SGs are associated with tumor cell survival, the effects of AEP and associated G3BP1 truncations were analyzed." (PMID 40858563, 2025). "This study highlights the crucial role of the BIN1/G3BP1/STAT1/CD8+ tumor-infiltrating lymphocyte signaling pathway in the progression of NSCLC and its mechanisms of immune evasion." (PMID 40346580, 2025). "In tumor cells, elevated expression of stress granule scaffold proteins, such as G3BP1, G3BP2, and TIA-1, is commonly observed, contributing to robust stress granule assembly in response to cellular stress." (PMID 41191214, 2025). "Correspondingly, compared with the BIN1-KO group, the BIN1-KO + sh-G3BP1 group exhibited a significantly reduced positive rate of G3BP1 expression in tumor tissues, whereas the positive rate of STAT1 expression was markedly increased." (PMID 40346580, 2025). "Emerging evidence indicates that membraneless organelles stress granules (SGs), whose assemblies are driven by scaffold protein G3BP1, are extensively involved in tumor, especially in OS." (PMID 40858563, 2025).
tumor (continued). "This interaction results in the increased expression of G3BP1 protein, facilitates SGs assembly, and plays a role in regulating cancer cell growth and proliferation, thereby expediting tumor development." (PMID 38383403, 2024). "Tumor‐cell surface MHC‐I is essential for the recognition of tumor cells by cytotoxic T lymphocytes (CTLs); therefore, we assessed the effect of G3BP1 on immune evasion." (PMID 38084438, 2024). "IHC scores exhibited that G3BP1 protein had an obvious increase in ESCC tumor samples compared to that in normal esophageal mucosa." (PMID 38906857, 2024). "Similar to USP21, higher protein levels of G3BP1 were found in ESCC tissues with T3-4 or N1-3 when compared to tumor samples with T1-2 or N0." (PMID 38906857, 2024). "Collectively, our study manifested the tumor-promoting regulation of the USP21/G3BP1 axis in ESCC progression." (PMID 38906857, 2024). "Employing subcutaneous tumorigenesis in nude mice and a metastatic tumor model, we incontrovertibly demonstrated G3BP1's contributory role in promoting proliferation and migration in vivo." (PMID 38164170, 2024). "Among other mRBPs, G3BP1 attracted our interest due to its unexplored role in tumor immune evasion and BLCA progression." (PMID 38084438, 2024). "Further molecular studies demonstrated that the USP21/G3BP1 axis played a tumor-promoting role in ESCC progression by activating the Wnt/β-Catenin signaling pathway." (PMID 38906857, 2024). "The G3BP1-SPOP bound ubiquitin activates AR signalling and upregulates G3BP1 transcription, leading to overexpression of G3BP1 in PCa tumour cells and further inhabitation of the tumour suppressor SPOP." (PMID 37749167, 2024). "EMT markers Cadherin, Vimentin, Snail and Slug are suppressed under SG core component G3BP1 depletion, implying the role of G3BP1 in tumor metastasis." (PMID 38110976, 2023). "Compared with normal cell, SG-related components are upregulated in various tumor cell, including G3BP1 and G3BP2." (PMID 37179344, 2023). "Analyses of these datasets further reveals YB-1, HIF1A, CAIX and G3BP1 transcript levels to be increased in tumours with amplified AKT1 and/or increased AKT1 expression." (PMID 34294889, 2022). "YB-1 has also been shown to promote stress-induced stress granule (SG) formation in pancreatic and colon cells, and we have demonstrated that, in multiple human tumour cell types, this involves the translational activation of G3BP1 mRNAs." (PMID 34294889, 2022). "The expression of NSUN2 is upregulated in HCC, which promotes tumor progression by increasing the expression level of H19 imprinted maternally expressed transcript (H19) and promoting the binding of H19 to G3BP stress granule assembly factor 1 (G3BP1)." (PMID 36120301, 2022). "G3BP1 is also closely related to the occurrence and development of tumors, G3BP1 was expressed in embryos and in different mature tissues under normal circumstances, and it also was highly expressed in tumor cells." (PMID 35935992, 2022). "Similar results were found for GANAB vs. GEMIN5, both of which are located within G3BP1 genomic loci and also driven by copy number alterations in tumor." (PMID 35879690, 2022). "Compared with the control group, G3BP1 knockdown inhibited their pro-tumor effects of MDMs-M2 in vitro and in vivo." (PMID 36291863, 2022).
tumor (continued). "Whereas SGs suppress cell death, making G3BP1 pro-tumorigenic, mTORC1 inhibition at lysosomes rather highlights the G3BPs as tumor suppressors." (PMID 34778262, 2021). "G3BP1 is potentially capable of enhanced tumor formation with highly proliferative phenotypes in other cancers." (PMID 34795264, 2021). "G3BP1 inhibition also prolongs tumor-free survival and represses tumor growth in a subcutaneous in vivo model derived from a TSC2-deficient renal tumor." (PMID 34778262, 2021). "Our studies reveal a unique oncogenic role of stress responsive protein G3BP1 that negatively regulates tumor-suppressive SPOP ubiquitin ligase, leading to upregulation of AR signaling and prostate tumorigenesis." (PMID 34795264, 2021). "Our data reveal that G3BP1 is required for SASP expression and that SASP secretion is a primary mediator of senescence-associated tumor growth." (PMID 33020468, 2020). "G3BP1 has been shown to play critical roles in innate immunity, tumor development and RNA metabolism." (PMID 31501480, 2019). "The results showed that YBX1 or G3BP1 overexpression significantly (p < 0.01) promoted tumor cell migration and invasion in RCC ACHN cells, while SPP1 depletion strongly attenuated the effect of YBX1 or G3BP1 induced RCC cells migration and invasion." (PMID 31481087, 2019). "Consistently, our in vivo orthotopic tumor xenografts results confirmed that knockdown of G3BP1 suppressed RCC tumor metastasis in mice." (PMID 31481087, 2019). "To further confirm the functional correlation between YBX1 and G3BP1 in vivo, we performed xenograft tumor experiments." (PMID 31481087, 2019). "Collectively, the results from the in vivo tumor xenograft models indicated that silencing of G3BP1 suppresses RCC tumor cell metastasis through YBX1/G3BP1-SPP1 signaling pathway." (PMID 31481087, 2019). "The results showed that G3BP1 downregulation led to the decrease of tumor cell invasion in the Matrigel invasion assay." (PMID 29717134, 2018). "Collectively, our findings support the notion that G3BP1 promotes tumor progression and metastasis through IL-6/G3BP1/STAT3 signaling axis in RCC." (PMID 29717134, 2018). "Together, our findings support a notion that G3BP1 promotes tumor progression and metastasis through IL-6/G3BP1/STAT3 signaling axis in RCC." (PMID 29717134, 2018). "Meanwhile, no significant (p > 0.05) associations were identified between the expression of G3BP1 and any other clinicopathological characteristics, including patient’s age, gender, RCC subtype, tumor size, tumor side, and necrosis." (PMID 29717134, 2018). "Our findings suggest G3BP1 as a novel mediator of RCC tumor progression and further extends the current knowledge about IL-6/STAT3 associated mechanism in RCC carcinogenesis." (PMID 29717134, 2018). "Consistently, our in vivo orthotopic tumor xenografts results also confirmed that knockdown of G3BP1 suppressed RCC tumor growth and metastasis in mice." (PMID 29717134, 2018). "Functionally, we found that knockdown of G3BP1 led to inhibition of tumor cell proliferation, migration, and invasion, as well as alterations of EMT markers using in vitro RCC cell line model." (PMID 29717134, 2018). "In summary, the expression of G3BP1 is significantly higher in RCC comparing to para-tumor normal tissues, and knockdown of G3BP1 significantly decreased tumor cell growth and metastasis in vitro and in vivo." (PMID 29717134, 2018). "Taken together, G3BP1 is an important molecule not only involved in controlling tumor cell growth, but also in mediating EMT in RCC." (PMID 29717134, 2018). "Aside from these in vitro experiments on the G3BP1-induced EMT, we evaluated the G3BP1-mediated regulation of primary tumor metastasis in vivo." (PMID 25962958, 2015). "Taken together, these data suggested that the downregulation of G3BP1 suppressed 4T1 tumor growth and metastasis in vivo." (PMID 25962958, 2015).
tumor (continued). "In concordance with the effect on cell growth, G3BP1, but also G3BP2 has been reported to be up-regulated in various tumor types and higher levels of G3BP1 have been reported in proliferating retinal epithelial cells." (PMID 24321297, 2013). "The region of RasGAP (amino acids 317–326) thought to bind to G3BP1 corresponds exactly to the sequence within fragment N2, a caspase-3-generated fragment of RasGAP, that mediates sensitization of tumor cells to genotoxins." (PMID 22205990, 2011). "G3BP1 activates the NF-κB signaling pathway at the level of phosphorylation through cyclic GMP-AMP synthase (cGAS), thereby facilitating senescence-associated tumor growth." (PMID 41513625, 2026). "Among the top‐hit mRBPs, Ras GTPase‐activating protein‐binding protein 1 (G3BP1), an mRBP known for assembling stress granules, attracted our interest because of its unknown implication in tumor immune evasion." (PMID 38084438, 2024). "Moreover, in vivo G3bp1 knockdown in MB49 cells decreased the tumor volume and weight and enhanced the infiltration of CD8+ T cells into tumor." (PMID 38084438, 2024). "In addition, ESCC samples with poor differentiation (G3) showed upregulated G3BP1 protein levels compared to tumor tissues with well/moderate differentiation (G1-2)." (PMID 38906857, 2024). "Consistently, IHC for xenograft tumor section indicated that the protein levels of Ki-67 and G3BP1 in USP21WT-expressing group were obviously upregulated compared with those in vector control, while USP21WT-induced increase of these proteins was greatly diminished by DSF treatment." (PMID 38906857, 2024). "Additionally, disulfiram (DSF), an inhibitor against USP21 deubiquitylation activity, markedly abolished the USP21-mediated stability of G3BP1 protein and significantly displayed an anti-tumor effect on USP21-driving ESCC progression." (PMID 38906857, 2024). "Interestingly, researchers have identified two anti-tumor drugs targeting G3BP1—resveratrol and epigallocatechin gallate (EGCG)." (PMID 37179344, 2023). "In age-related tumors, G3BP1 activates the NF-κB and STAT3 pathways via cyclic GMP-AMP synthase (cGAS), promoting the senescence-associated secretory phenotype (SASP) and stimulating the migration of tumor cell." (PMID 37179344, 2023). "G3BP1 has been reported to trigger tumor metastasis via mediating the cellular stress responses." (PMID 36291863, 2022). "In addition, transwell migration and invasion assays showed that circEIF3H overexpression markedly ameliorated the tumor-suppressive effect of HSPD1/RBM8A/G3BP1 silencing." (PMID 35568705, 2022). "We next found that USP10 coordinately promotes tumor progression with G3BP1." (PMID 34967276, 2022). "Elevated levels of HIF1A, its target CAIX, and VEGFA transcripts are also seen in tumours with a gain of function or amplification of YB-1, although this was not the case for G3BP1 or NFE2L2 (encoding NRF2)." (PMID 34294889, 2022). "Furthermore, high expression of G3BP1 correlates with high expression of Rhoc, which has an important role in cytoskeleton formation and reconstruction and is closely related to tumor metastasis." (PMID 36330442, 2022). "Furthermore, in vivo orthotopic tumor xenografts results confirmed that downregulation of G3BP1 expression inhibited RCC tumor growth and metastasis in mice." (PMID 36330442, 2022). "Altogether, our study elucidates the tumor-promoting function of KPNB1 through upregulating G3BP1." (PMID 35902727, 2022).
tumor (continued). "The immunohistochemical data showed lower expression of G3BP1, CCL13 and CD206 in the group of mice implanted with SAS cells mixed with G3BP1-knockdown MDMs-M2 than in the control group, and smaller tumor sizes were observed in G3BP1-depleted group as revealed by H&E staining." (PMID 36291863, 2022). "The intensity of G3BP1 staining was higher in tumors compared with non-tumor lung sections." (PMID 34521423, 2021). "In addition, G3BP1 has been reported to be involved in regulating various signalling pathways and plays a vital role in tumour development and progression." (PMID 33579337, 2021). "Previously, we found a link between G3BP1, SGs and tumor progression." (PMID 32406909, 2020). "Methylated H19 RNA may compete with MYC mRNA for binding to G3BP1, promoting tumor cell progression." (PMID 32978516, 2020). "Here, the authors show that G3BP1 is required for the induction of the senescence-associated secretory phenotype (SASP), without affecting senescence, and that SASP secretion is a primary mediator of senescence-associated tumour growth." (PMID 33020468, 2020). "However, G3BP1-depleted senescent WI-38 cells were unable to promote tumor growth when compared to control senescent WI-38 cells." (PMID 33020468, 2020). "Additionally, we investigated the association of YBX1, G3BP1 and SPP1 expression with several clinical parameters including gender, age, tumor size, TNM stage and Fuhrman grade." (PMID 31481087, 2019). "Moreover, YB‐1‐K81A rescued EwS metastasis to lungs, which correlated with re‐expression of NRF2, G3BP1, and HIF1α in tumor tissues." (PMID 31668005, 2019). "Interestingly, bioluminescent signals indicated that mice implanted with G3BP1 knockdown group had much smaller tumor and fewer liver and lung metastatic foci detected than those in scramble controls." (PMID 31481087, 2019). "In addition, in vivo orthotopic tumor xenografts results confirmed that knockdown of G3BP1 suppressed RCC tumor growth and metastasis in mice." (PMID 29717134, 2018). "In cultured RCC cells, knockdown of G3BP1 results in inhibition of tumor cell proliferation, migration, and invasion, consistently with the alteration of epithelial–mesenchymal transition (EMT) and cell proliferative markers, including Cadherins, Vimentin, Snail, Slug, c-Myc, and cyclin D1." (PMID 29717134, 2018). "Collectively, the results from in vivo tumor xenografts model indicated that silencing of G3BP1 could suppress RCC tumor cell growth as well as inhibit RCC cell metastasis to liver and lung." (PMID 29717134, 2018). "We therefore investigated whether the known functions attributed to G3BP1 could be modulated by TAT-RasGAP317–326 and whether G3BP1 was required for the peptide to sensitize tumor cells to genotoxin-induced apoptosis." (PMID 22205990, 2011). "This interaction might nevertheless occur and one could hypothesize that TAT-RasGAP317–326 sensitizes tumor cells by modulating G3BP1 functions by either inhibiting the binding of RasGAP to G3BP1 or by mimicking the binding of RasGAP to G3BP1." (PMID 22205990, 2011). "To unequivocally determine whether G3BP1 is needed for TAT-RasGAP317–326-mediated tumor sensitization, we used tumor cells in which G3BP1 was silenced and transformed MEFs from G3BP1 knock-out mice." (PMID 22205990, 2011). "Furthermore, G3BP1 knockout significantly attenuated 22RV1 xenograft tumor formation and growth." (PMID 35252555, 2022). "Also, knockdown of G3BP1 was reported to prevent tumor invasion and metastasis in xenograft model." (PMID 29717134, 2018). "IHC analysis further demonstrated a significant reduction in the positive rates of G3BP1 expression and upregulation in the positive rates of STAT1 expression within tumor tissues in the BIN1-WT + sh-G3BP1 group compared to the BIN1-WT group." (PMID 40346580, 2025).